INS (insulin)
Diseases named in the same sentence as INS in open-access papers (continued):
Sharing a sentence is not in itself a finding about the gene and the disease.
Insulin resistance (continued). "In addition, insulin signaling in insulin target tissues (liver, skeletal muscle, and adipose tissue) is weakened by the burden of glucose toxicity, leading to the development of insulin resistance." (PMID 33322512, 2020). "Finally, a meta-analysis of clinical trials revealed that in T2D patients, daily supplementation with RSV ≥ 100 mg significantly improved the fasting plasma glucose and insulin levels, homeostasis model assessment of insulin resistance (HOMA-IR) index." (PMID 32397353, 2020). "The present study shows that SPs suppressed Px-induced disruption of glucose metabolism by potentiating insulin secretion and reducing insulin resistance in lean type 2 diabetic rats, and suggests SPs have potential use as anti-diabetic agents in Asian type 2 diabetes." (PMID 31991596, 2020). "In the same study, PFOA was also associated with insulin secretion, although none of the measured PFASs were associated with insulin resistance." (PMID 33182712, 2020). "Thus, considering the potential involvement of T in regulating insulin sensitivity, a compensatory increase in the expression of androgen receptor in a setting of insulin resistance in HH and T2DM is expected." (PMID 33537005, 2020). "Increased free radicals might contribute to insulin resistance via increased free fatty acids oxidation, reduction of glucose uptake by the muscle, and impaired insulin release." (PMID 33171699, 2020). "In both groups, the participants gained weight, and fasting insulin levels were likely increased due to seasonal fluctuations from summer to winter, suggesting that the deterioration of insulin resistance and glucose tolerance was suppressed by ingesting OLL2712 cells." (PMID 32023901, 2020). "Furthermore, the alb-SREBP-1c mice displayed hepatic insulin resistance and had higher levels of plasma insulin, leptin, triglycerides, and free fatty acids versus C57Bl6 mice." (PMID 32532003, 2020). "T2D, often combined with obesity, induces hormonal changes by increasing insulin resistance, inflammation with increased Interleukin 6, and increased reactive oxygen species, all of which can lead to hyperinsulinemia and insulin-stimulated mitosis by directly affecting cancer cell proliferation." (PMID 32369516, 2020). "Thus, the homeostatic model assessment of insulin resistance (HOMA IR) was evaluated as the insulin-sensitive range." (PMID 32650579, 2020). "Both inadequate pancreatic insulin secretion and increased circulating levels of glucose due to sleep deprivation could lead to the development of insulin resistance and type 2 diabetes." (PMID 31998805, 2020). "Particularly, CRLS1, a primary mediator in the activation and recruitment of thermogenic fat correlates positively with insulin sensitivity and could reduce insulin resistance in MetS." (PMID 32340411, 2020). "However, after 36 weeks of the disease, the DM mice exhibited significantly decreased serum insulin levels compared with that of the control mice, possibly because of long-term insulin resistance." (PMID 32194828, 2020). "In our study, 30 min and 1-h post-load glucose and 2-h insulin were independently associated with retinopathy, however, we did not confirm such association with insulin resistance indicators." (PMID 33091029, 2020). "Furthermore, ROS reduces insulin signalling and induces subsequent insulin resistance, yielding elevated FoxO1 activation." (PMID 33108705, 2020). "However, how GR or GRα results in insulin resistance via affecting the insulin signalling pathway is poorly understood." (PMID 32792855, 2020). "In turn, mTOR and p70S6K are enzymes that integrate many cell signaling pathways, including the insulin one, the dysregulation of which may be involved in the pathogenesis of insulin resistance and type 2 diabetes." (PMID 32917052, 2020).
Insulin resistance (continued). "Oleate should even have a protective benefit against palmitate-induced insulin resistance and might enhance the mitochondrial function, protecting against apoptosis, and increasing insulin sensitivity." (PMID 32947855, 2020). "In conditions of insulin resistance, β-cells initially undergo a phase of adaptation, in that they enhance their insulin secretory capacity and increase their size and number to cope with the insulin demand." (PMID 32150819, 2020). "Together, hyperglycemia and insulin resistance may also alter mitochondrial function, and insulin action can be impaired by cytokines in response to metabolic stress." (PMID 32927712, 2020). "Because we showed both higher glucose and insulin-stimulated levels in subjects carrying the Hp2-2 phenotype, we can hypothesize that hyperinsulinemia is secondary to subtle peripheral insulin resistance in feeding conditions." (PMID 32695161, 2020). "Efficacy assessments were made by measuring fasting glucose, postprandial glucose, fasting insulin, homeostasis model assessment for insulin resistance (HOMA-IR), C-peptide, glycosylated hemoglobin, lipid metabolism indicators, and physical metrics, along with safety assessments." (PMID 32085495, 2020). "One could expect also alterations in insulin signaling in the adipose tissue, but we can postulate that the mechanisms behind insulin resistance development might be different depending on the type of diet consumed and the time of exposure to the diets." (PMID 32411098, 2020). "Certain (poly)phenols, as supplements or in foods, can improve insulin resistance by several mechanisms including lowering postprandial glucose, modulating glucose transport, affecting insulin signalling pathways, and by protecting against damage to insulin-secreting pancreatic β-cells." (PMID 33066504, 2020). "Cinnamon can increase insulin sensitivity and reduce insulin resistance." (PMID 32846751, 2020). "The Kaplan–Meier curve comparing the effects on lifespan of Pio to the stimulator of insulin secretion glimepiride, which is extensively prescribed for the treatment of insulin resistance, demonstrated that patients on Pio have increased survival compared to those on glimepiride." (PMID 33219735, 2020). "Even though heart failure is associated with states of insulin resistance like type II diabetes, the role of cardiac tissue insulin signaling in the context of heart failure is not clear." (PMID 33184414, 2020). "Preclinical and clinical studies have shown that PDE5 inhibition has a beneficial effect not only on improving β cell function but also on increasing insulin sensitivity of other peripheral tissues (skeletal muscle cells, adipocytes, and endothelial cells), thus improving insulin resistance." (PMID 33153226, 2020). "Concurrently, a recent study showed that the short-term insulin exposure can improve neuroprotection against excitotoxicity and prevent glutamate mediated excitotoxicity whereas chronic insulin exposure results in neuronal insulin resistance and worsen excitotoxicity." (PMID 32971941, 2020). "Regarding insulin sensitivity, obese (SL-HFD) males displayed insulin resistance, defined by significantly higher AUC during the insulin tolerance test (ITT) values than in lean (NL-CD) males, but GNX did not worsen insulin sensitivity neither in NL-CD or SL-HFD conditions." (PMID 33107844, 2020). "Additionally, correlation analysis demonstrated that plasma MaR1 levels were significantly correlated with parameters regarding obesity, glucose metabolism, lipid profiles, insulin secretion, and insulin resistance." (PMID 32377160, 2020). "Notably, dietary-induced changes of plasma MDA and NT were associated with changes of fasting insulin, HOMA-IR, and HbA1c, suggesting an important role of oxidative damage in the regulation of beta-cell function and insulin resistance via multiple mechanisms." (PMID 31926623, 2020).
Insulin resistance (continued). "Furthermore, adjustments for fasting insulin as well as HOMA-IR attenuated the association between RHI and incident type 2 diabetes, suggesting a possible mediating role of insulin resistance." (PMID 32690629, 2020). "These fatty acid metabolites have been hypothesised to be involved in the development of insulin resistance, via impairment of insulin signalling and reduced insulin-stimulated glucose uptake by skeletal muscle." (PMID 32971810, 2020). "These hormones are key regulators of glucose and lipid homeostasis maintenance, high levels of glucocorticoids can produce insulin resistance by reducing insulin-dependent glucose uptake, improving hepatic gluconeogenesis and inhibiting insulin secretion from pancreatic cells." (PMID 32258479, 2020). "The lipogenic features of fructose lead to the development of NAFLD and, as a consequence, to increased hepatic insulin resistance, a disorder worsened by the lower satiety signal derived from fructose metabolism compared to glucose due to the weaker impact on insulin secretion." (PMID 32591906, 2020). "Similarly, all drug-intervention groups also showed significantly reduced fasting plasma insulin level (P < 0.01, Wilcoxon rank sum test) as well as homeostatic model assessment-insulin resistance (HOMA-IR) (P < 0.01, Wilcoxon rank sum test)." (PMID 33359679, 2020). "Furthermore, it was shown that gallic acid and p-coumaric acid (TP17) ameliorate insulin shortage and insulin resistance." (PMID 33150068, 2020). "FBG and fasting insulin reflect the level of insulin resistance." (PMID 33015194, 2020). "Although in vitro and in vivo studies indicate that the change in [pH]i causes insulin resistance, the mechanisms by which drop in [pH]i contributes to decrease insulin responses are not clearly defined." (PMID 32977552, 2020). "We found that HFD consumption led to insulin resistance, as evidenced by increased fasting glucose and insulin concentration, impaired glucose tolerance, reduced insulin responsiveness, an increase in HOMA-IR and decreased muscular glucose uptake compared to the control group." (PMID 33036203, 2020). "Two studies also assessed various markers of insulin resistance (IR) [e.g. Matsuda index and homeostasis model assessment of insulin (HOMA-IR, HOMA S)] and beta cell function [e.g. insulin sensitivity index 2 (ISSI-2), insulinogenic index (IGI)/HOMA-IR, and HOMA B]." (PMID 33168031, 2020). "Finally, insulin-mediated suppression of hepatic gluconeogenesis occurs in insulin resistance-state." (PMID 32932777, 2020). "SFRP2 methylation in tumor area was decreased in patients who had higher levels of vitamin D. SFRP2 promoter methylation was positively correlated in tumor area with insulin and homeostasis model assessment of insulin resistance (HOMA-IR) but negatively correlated with HDL-c." (PMID 32517740, 2020). "ROCK1 also interferes with insulin signaling to increase blood glucose levels and ROCK1 overactivity is associated with metabolic disease states and related comorbidities including obesity, insulin resistance, and dyslipidemia." (PMID 33633690, 2020). "The results indicated an excess of epinephrine could affect glucose intolerance mainly by impaired secretion of insulin and that of norepinephrine could affect glucose intolerance mainly by increased insulin resistance." (PMID 33324347, 2020). "Third, we did not have data on insulin levels, thus, the association between insulin resistance, such as homeostasis model assessment insulin resistance and Cre/BW ratio, was unclear." (PMID 31952309, 2020). "Stress hyperglycemia may be induced by a decrease of both insulin secretion and the worsening of insulin resistance; it may produce organ damage by inducing endothelial dysfunction and thrombosis through the glycation process and oxidative stress generation." (PMID 33425939, 2020).
Insulin resistance (continued). "The last studied protein resistin promotes 3T3-L1 preadipocyte differentiation and is an important mediator of obesity-induced insulin resistance; moreover, this protein could be secreted by adipocytes and is involved in insulin regulation." (PMID 32463311, 2020). "We hypothesize that the increased expression of this insulin sensitizing genes acts as a counter mechanism to contrast the hyperinsulinemia-induced insulin resistance." (PMID 32718202, 2020). "It seems well established that insulin resistance may increase tau pathology by interfering the balance between tau kinases and phosphatases Tau also modulates insulin signaling, contributing to the cross-talk between both pathologies." (PMID 32264944, 2020). "To determine the ability of E2 and P4 supplementation to prevent HFD-induced disturbances in insulin sensitivity and glucose tolerance, we calculated the homeostatic model of insulin resistance (HOMA-IR) from fasted insulin concentration and performed intraperitoneal GTT in OVX mice." (PMID 32635208, 2020). "Most importantly, there is mounting evidence that vitamin D supplementation could reduce the chance of presenting IFG and T2DM by improving β cell function and insulin sensitivity and lowering fasting insulin, HbA1c, and insulin resistance." (PMID 33396618, 2020). "For example, adipocyte-specific ablation of GLUT4, the primary glucose transporter responsible for insulin-stimulated glucose uptake in AT and muscle, impairs insulin signalling in liver and muscle, and induces systemic insulin resistance and glucose intolerance in mice." (PMID 33292104, 2020). "Similarly, evidence from in vivo animal studies indicates that elevation of insulin levels by exogenous insulin administration results in insulin resistance." (PMID 32230718, 2020). "Increased FFA levels due to lipid metabolic disorders are known to induce inflammation associated with insulin resistance and T2DM mechanism, reducing glucose uptake, increasing hepatic glucose production, impairing insulin signaling pathways, and causing adipokine secretion disorders." (PMID 33266423, 2020). "Fasting blood sugar, insulin, homeostatic model assessment of insulin resistance, lipid profile, high-sensitivity C-reactive protein, total antioxidant capacity, malondialdehyde and gastrointestinal symptoms were measured in all of the subjects at baseline and postintervention." (PMID 32503652, 2020). "Similarly, 3-bromo-4,5-bis(2,3-dibromo-4,5-dihydroxybenzyl)-1,2-benzenediol isolated from the red alga Rhodomela confervoides was able to activate insulin signaling and prevent palmitate-induced insulin resistance by intrinsic PTP1B inhibition (IC50 2.0 μM)." (PMID 33007997, 2020). "Similar to neurons, chronic insulin exposure to macrophages can induce insulin resistance." (PMID 33100956, 2020). "Interestingly, within obese subjects, those with insulin resistance and hyperinsulinemia were shown to have higher levels of Hcy than obese insulin-sensitive individuals." (PMID 32645905, 2020). "This may be determined by the improvement of angiotensin II-related insulin-resistance, as evidenced by reduction of insulin levels and by improvement of glucose parameters." (PMID 32033349, 2020). "Therefore, most of the T2D patients have chronically elevated plasma FFA levels that lead to insulin resistance in muscle and liver and impairs insulin secretion in the pancreas." (PMID 32397353, 2020). "The insulin signal pathway is closely related to the occurrence of insulin resistance." (PMID 32964053, 2020). "Furthermore, FGF21 acts as an insulin sensitizer in mice to overcome peripheral insulin resistance induced by fasting in mice, an effect that is decreased in BAT of liver-specific FGF21 KO mice." (PMID 31918921, 2020). "Animal studies showed that injection of RBP4 in normal mice leads to insulin resistance while genetic deletion of RBP4 gene could enhance insulin sensitivity." (PMID 31921323, 2020).
Insulin resistance (continued). "Increasing insulin secretion and reducing insulin resistance could improve glucose regulation, restore intestinal microbiome disorders and maintain the homeostasis of the gut microbiota." (PMID 32281722, 2020). "TNF-α leads to insulin resistance by means of phosphorylation of serine residues of the insulin receptor substrate-1, preventing the receptor substrate from binding to the insulin receptor, and inhibiting insulin action." (PMID 32947869, 2020). "The insulin resistance of the syndrome seems to be characterized by a defect in tissue availability or utilization of inositol mediator; therefore, the supplementation of that mediator would improve the intracellular effect of insulin." (PMID 32646482, 2020). "Evidence strongly supports the role of insulin resistance in cognitive decline and it has been suggested that an insulin sensitizer may prevent against cognitive decline in pre-diabetic and diabetic patients." (PMID 32697764, 2020). "Endoplasmic reticulum (ER) stress is known to participate in the development of insulin resistance in liver, mainly by promoting the accumulation of lipids in the liver, by directly blocking insulin signaling, and by modifying the expression of key enzymes of gluconeogenesis or lipolysis." (PMID 32668665, 2020). "In addition, hyperinsulinemia and insulin resistance contribute to vascular abnormalities since the balanced endothelium-dependent vasodilator and vasoconstrictor effects of insulin are shifted towards predominant vasoconstriction in obesity." (PMID 31991894, 2020). "We hypothesize that carrageenan-induced effects on insulin signaling and inflammation contribute to glucose intolerance and insulin resistance." (PMID 32377523, 2020). "As elevated levels of both ceramide and choline result in insulin resistance in mice we targeted these intermediates to establish if alterations in their serum levels could explain the insulin sensitive phenotype in Phospho1−/− mice." (PMID 33092598, 2020). "Excessive iron affected the synthesis and secretion of insulin, and enhances lipid oxidation, thereby reducing glucose utilization in muscles and increasing gluconeogenesis in the liver, leading to liver-mediated insulin resistance." (PMID 33042010, 2020). "Though lipid/obesity induced insulin resistance is well examined, the mechanism(s) linking activity to insulin sensitivity is largely unknown, particularly in aging." (PMID 32098447, 2020). "Interestingly, GRb1 downregulated the levels of fasting plasma glucose and fasting serum insulin, decreased the area under the curve, and improved insulin resistance." (PMID 32733933, 2020). "Obesity associated with insulin resistance and glucose intolerance can progress to diabetes when the pancreas no longer produces sufficient insulin levels." (PMID 31903726, 2020). "Moreover, it has suggested that imeglimin corrects three fundamental defects commonly observed in patients with T2DM, including a higher rate of gluconeogenesis, low glucose-induced insulin secretion from beta cells, and peripheral insulin resistance." (PMID 32215274, 2020). "TBS had an inverse relationship with HbA1c, insulin, and insulin resistance unrelated to weight." (PMID 32503328, 2020). "Complementary measurements of insulin resistance and insulin levels revealed that the impairment of glucose tolerance in apoE4 mice maintained on a control diet is parallel to impairments in insulin tolerance and insulin secretion." (PMID 32075060, 2020). "Some studies suggest a primary role of oxidative muscle fibers in insulin resistance, while others reported a similar insulin resistance in different muscle fibers although different muscle fibers appear to have similar sensitivity for phosphoregulation by insulin." (PMID 32612543, 2020). "Insulin signaling pathway dysregulation or insulin resistance is the main reason for T2D." (PMID 33042976, 2020).